MAPRE1 (microtubule associated protein RP/EB family member 1)
Description:
Plus-end tracking protein (+TIP) that binds to the plus-end of microtubules and regulates the dynamics of the microtubule cytoskeleton. Recruits other +TIP proteins to microtubules by binding to a conserved Ser-X-Leu-Pro (SXLP) motif in their polypeptide chains. Promotes cytoplasmic microtubule nucleation and elongation. Involved in mitotic spindle positioning by stabilizing microtubules and promoting dynamic connection between astral microtubules and the cortex during mitotic chromosome segregation. Assists chromosome alignment in metaphase by recruiting the SKA complex to the spindle and stabilizing its interactions with microtubule bundles (K-fibers). Also acts as a regulator of minus-end microtubule organization: interacts with the complex formed by AKAP9 and PDE4DIP, leading to recruit CAMSAP2 to the Golgi apparatus, thereby tethering non-centrosomal minus-end microtubules to the Golgi, an important step for polarized cell movement. Promotes elongation of CAMSAP2-decorated microtubule stretches on the minus-end of microtubules. Acts as a regulator of autophagosome transport via interaction with CAMSAP2. Functions downstream of Rho GTPases and DIAPH1 in stable microtubule formation (By similarity). Promotes microtubule-mediated GJA1/CX43 trafficking to cell membranes via its interaction with DSP, thereby facilitating gap junction intracellular communication. May play a role in cell migration (By similarity).
Synonyms: EB1
Tractability: Small molecule: a structure with a bound ligand is known; it has a binding pocket of medium quality. PROTAC: ubiquitination databases record sites on it; its protein half-life has been measured.
Gene: Protein-coding gene on chromosome 20 (32,819,769 to 32,856,284, forward strand). Ensembl gene ENSG00000101367.
Subcellular location: Cytoplasm, cytoskeleton; Cytoplasm, cytoskeleton, microtubule organizing center, centrosome; Golgi apparatus; Cytoplasm, cytoskeleton, spindle; Cytoplasm, cytoskeleton, spindle pole; Cell membrane
Subcellular location (Human Protein Atlas): Centrosome; Cytosol; Basal body
Pathways (Reactome):
Cell Cycle: AURKA Activation by TPX2; Amplification of signal from unattached kinetochores via a MAD2 inhibitory signal; EML4 and NUDC in mitotic spindle formation; Loss of Nlp from mitotic centrosomes; Loss of proteins required for interphase microtubule organization from the centrosome; Mitotic Prometaphase; Recruitment of NuMA to mitotic centrosomes; Recruitment of mitotic centrosome proteins and complexes; Regulation of PLK1 Activity at G2/M Transition; Resolution of Sister Chromatid Cohesion; Separation of Sister Chromatids; The role of GTSE1 in G2/M progression after G2 checkpoint
Organelle biogenesis and maintenance: Anchoring of the basal body to the plasma membrane
Signal Transduction: RHO GTPases Activate Formins
Gene Ontology:
Molecular function: cadherin binding; identical protein binding; microtubule plus-end binding; protein binding; protein serine/threonine kinase binding; RNA binding; microtubule binding
Biological process: attachment of mitotic spindle microtubules to kinetochore; cell migration; establishment of mitotic spindle orientation; negative regulation of microtubule polymerization; positive regulation of microtubule polymerization; positive regulation of protein localization; protein localization to astral microtubule; protein localization to microtubule; protein localization to mitotic spindle; intracellular protein localization; regulation of microtubule polymerization or depolymerization; spindle assembly; microtubule bundle formation; microtubule polymerization
Cellular component: centrosome; ciliary basal body; cortical microtubule cytoskeleton; cytoplasm; focal adhesion; Golgi apparatus; microtubule; mitotic spindle astral microtubule end; mitotic spindle microtubule; mitotic spindle pole; plasma membrane; spindle; cytosol; microtubule plus-end; spindle midzone; cell projection membrane; cytoskeleton; microtubule cytoskeleton; spindle pole
Genetic constraint (gnomAD): Loss-of-function variants: 5 observed, 27.95 expected, observed/expected ratio (o/e) 0.18, 90% interval 0.093 to 0.38. The upper end of that interval is the gene's LOEUF score, 0.38, which puts it in group 1 of 6, group 1 being the genes least tolerant of losing a copy. Missense variants: 190 observed, 306.48 expected, observed/expected ratio (o/e) 0.62, 90% interval 0.55 to 0.7. Synonymous variants: 113 observed, 113.76 expected, observed/expected ratio (o/e) 0.99, 90% interval 0.85 to 1.16.
Homologues: Orthologues: chimpanzee MAPRE1 (100% identical), macaque MAPRE1 (99% identical), rabbit MAPRE1 (99% identical), guinea pig Mapre1 (98% identical), mouse Mapre1 (97% identical), rat Mapre1 (97% identical), pig MAPRE1 (93% identical), tropical clawed frog mapre1 (80% identical), zebrafish mapre1b (74% identical), zebrafish mapre1a (70% identical), Caenorhabditis elegans ebp-1 (51% identical), Caenorhabditis elegans ebp-2 (40% identical), and 1 more. Paralogues in human: MAPRE3 (69% identical), MAPRE2 (58% identical).
Diseases named in the same sentence as MAPRE1 in open-access papers:
MAPRE1 is named in the same sentence as 20 diseases in open-access papers, as found by Europe PMC text mining. Sharing a sentence is not in itself a finding about the gene and the disease. The quoted sentences say what the papers report.
colorectal cancer (4 papers, 2013 to 2020). A primary or metastatic malignant neoplasm that affects the colon or rectum. "MAPRE1 is another oncogenic target of miR-10b, known to regulate microtubule dynamics and a proposed biomarker of gastric and colorectal cancer." (PMID 30658617, 2019). "For example, in colorectal cancer, MAPRE1 binds to the tumor suppressor protein APC which is often mutated in familial and sporadic forms of colorectal cancer." (PMID 23822816, 2013). "LRG1 has been identified to be differentially expressed in colorectal cancer, and a panel of the CEA, IGFBP2, MAPRE1, and LRG1 proteins is potentially a prediagnostic marker in colorectal cancer plasma samples." (PMID 32337221, 2020).
gastric cancer (3 papers, 2019 to 2025). A primary or metastatic malignant neoplasm involving the stomach. "In stomach cancer, miR-10b acts as a tumor suppressor and targets microtubule-associated protein RP/EB family member 1 (MAPRE1)." (PMID 31110513, 2019). "As a tumor suppressor, miR-10b-5p targets the oncogenic proteins TIAM1 and MAPRE1 in gastric cancer cells." (PMID 39796267, 2025). "miR-10b-5p also epigenetically regulates MAPRE1, reinforcing its tumor-suppressive role in gastric cancer." (PMID 39796267, 2025). "Overexpression of MAPRE1 in gastric cancer cells is mainly involved in cell cycle-related functions." (PMID 32566649, 2020). "In gastric cancer, miR-10b-5p targets oncogenic proteins such as TIAM1 and MAPRE1, and its overexpression inhibits proliferation, migration, and invasion while inducing apoptosis, effectively modulating the TME to suppress tumor progression." (PMID 39796267, 2025). "In gastric cancer, miR-10b-5p functions as a TSmiR by targeting oncogenic proteins such as TIAM1 and MAPRE1." (PMID 39796267, 2025). "Its downregulation in gastric cancer tissues leads to increased expression of TIAM1 and MAPRE1." (PMID 39796267, 2025).
malignant melanoma (2 papers, 2024). "Previous research has shown miR-10a-5p’s involvement in inhibiting chicken granulosa cell proliferation by targeting MAPRE1 to suppress CDK2, as well as suppressing melanoma cell proliferation and migration." (PMID 38275797, 2024).
glioma (1 paper, 2022). A benign or malignant brain and spinal cord tumor that arises from glial cells (astrocytes, oligodendrocytes, ependymal cells). "To further verify the miR-526b-3p regulate glioma process through MAPRE1, we transfected the MAPRE1 vector in U87 and U251 cells." (PMID 35198024, 2022). "The results showed that MAPRE1 expression was increased in ADR-resistant glioma cells compared with the normal glioma cells." (PMID 35198024, 2022). "In line with the CCK8 assay results, flow cytometry results showed that MAPRE1 retarded the increase of apoptosis rate induced by miR-526b-3p within ADR-resistant glioma cells." (PMID 35198024, 2022). "Furthermore, overexpression miR-526b-3p inhibited tumor procession and increased the sensitivity of glioma to ADR through downregulating the expression of MAPRE1." (PMID 35198024, 2022). "Further, MAPRE1 levels within glioma tissues and ADR-resistant glioma tissues were analyzed." (PMID 35198024, 2022). "Consistently, increased expression of MAPRE1 in glioma cells was confirmed." (PMID 35198024, 2022). "Transwell assay results showed that MAPRE1 rescued the migration and invasion roles of miR-526b-3p in ADR-resistant glioma cells." (PMID 35198024, 2022).
lung carcinoma (1 paper, 2019). "Analogously, genes involved in wound healing and cell migration (i.e., SERPINE1, HMGCR, IGFBP5, and S100A14) or reported as prognostic factors in breast, ovarian, gastric, and lung cancers (i.e., MAPRE1, HSPA1B, and PPME1) were negatively modulated." (PMID 31752957, 2019).
muscle disorders (1 paper, 2020). "To further understand the differential involvement of ADNP in the various muscle disorders, we have also assessed the levels of the ADNP binding proteins EB1 (MAPRE1) and EB3 (MAPRE3)." (PMID 33086621, 2020).
psoriasis (1 paper, 2024). An autoimmune condition characterized by red, well-delineated plaques with silvery scales that are usually on the extensor surfaces and scalp. "Furthermore, this study marks the initial identification of several proteins—MAPRE1, SWAP70, VPS26A, BRD2, and B3GNT2—as potentially contributing factors in the pathogenesis of psoriasis." (PMID 39883516, 2024).
virus infection (1 paper, 2020). "Combining the protein functional analysis in the current study with previous reports, we also observed that MAPRE1 and VDAC1 were related to virus infection." (PMID 33329485, 2020).
tumor (9 papers, 2019 to 2025). "High levels of MAPRE1 are correlated with tumor malignancy, high histological grade, and poor clinical outcome." (PMID 35198024, 2022). "In ductal but not lobular tumors, significant inverse correlations were observed between the tumor levels of miR-10b and miR-30c and the mRNA levels of cancer-relevant target genes SRSF1, PIEZO1, MAPRE1, CDKN2A, TP-53 and TRA2B, as well as tumor grade." (PMID 30658617, 2019). "The three-marker panel of CLIC1, MAPRE1 and SERPINA3 exhibited significance regardless of tumor stage, grade, size, and menopausal status." (PMID 30963111, 2019). "Three genes consisting of CLIC1, MAPRE1, and SERPINA3 in the refined TGFβ signature significantly stratified overall survival (log-rank p = 0.0141) in a larger validation cohort irrespective of menopausal status, tumor stage, grade, and size." (PMID 30963111, 2019).
cancer (7 papers, 2014 to 2024). A tumor composed of atypical neoplastic, often pleomorphic cells that invade other tissues. "Moreover, MAPRE1 works as a diagnosis and prognosis biomarker in cancer." (PMID 35198024, 2022). "PPIN2 includes Dync1h, which does not appear closely related to cancer, but it also includes Mapre1." (PMID 39139811, 2024). "MiR-93 could be considered as a potential prognostic biomarker for PDAC, and miR-93 itself or its protein targets (CRMP2, MAPRE1, or YES1) have been elucidated as potential new therapeutic targets for this cancer." (PMID 32366853, 2020).
MAPRE1 also shares sentences with these, for which no sentence is quoted: adenoma (1 paper); breast carcinoma (1); clear cell renal carcinoma (1); colon cancer (1); ductal carcinoma (1); infection (1); memory impairment (1); nasopharyngeal carcinoma (1); Nephropathy (1); stomach cancer (1).